VEGFA (vascular endothelial growth factor A)
Diseases named in the same sentence as VEGFA in open-access papers (continued):
Sharing a sentence is not in itself a finding about the gene and the disease.
melanoma (continued). "We previously identified co-expression of CCL20, TNF, and VEGFA cytokines by tissue TAMs in an exploratory set of 7 metastasizing melanomas." (PMID 34439098, 2021). "Our study showed that MIR205HG enhanced melanoma growth and progression by targeting the miR-299-3p/VEGFA axis." (PMID 33535182, 2021). "It is well established that melanoma growth and progression depend on angiogenesis, and vascular endothelial growth factor A (VEGF-A) has been shown to be an important angiogenic driver in melanoma." (PMID 31915016, 2020). "In the present study, qPCR analyses revealed a higher expression of PTGS2 or VEGFA genes in hypoxia-treated breast and melanoma cells, respectively." (PMID 30788287, 2019). "Then, we confirmed that the mTOR/VEGFA pathway was activated during the process of kindlin-2-induced melanoma progression and angiogenesis." (PMID 31427543, 2019). "As expected, application of tRA together with the ATM inhibitor greatly reduced the VEGFA expression in melanoma xenografts." (PMID 31766690, 2019). "Mechanistically, melanoma cells with high levels of kindlin-2 promoted the secretion of VEGFA, a predominant inducer of both normal and pathophysiological angiogenesis." (PMID 31427543, 2019). "In view of this, bevacizumab, a humanized monoclonal antibody that neutralizes the VEGFA isoforms, is one of the most frequently investigated antiangiogenic molecules with a certain curative effect in melanoma." (PMID 31427543, 2019). "Several angiogenic stimulators have been shown to be important for initiation and maintenance of angiogenesis in melanoma, including VEGFA, interleukin-8 (IL-8), bFGF, and uPA." (PMID 29183378, 2017). "Transcriptomic study identified Basic fibroblast growth factor (bFGF), GRO1 oncogene (GROα, CXCL1), IL-8 and Vascular endothelial growth factor A (VEGF-A) to participate in such an effect of melanoma cells on keratinocytes." (PMID 29236046, 2017). "In Kaposi’s sarcoma, prostate cancer, lung cancer and melanoma, it mimics the effect of vascular endothelial growth factor A (VEGFA) and confers resistance to anti-VEGF therapy." (PMID 29258207, 2017). "In most of the clinical trials evaluating the effect of antiangiogenic treatment in patients with malignant melanoma, agents targeting the vascular endothelial growth factor A (VEGF-A) pathway have been used." (PMID 27756886, 2016). "In human melanoma cells, acidic pH increases the expression of the proangiogenic factors VEGFA and IL8." (PMID 27078157, 2016). "Secretion of vascular endothelial growth factor-A (VEGF-A) by melanoma cells has been correlated to the transition from the radial to the vertical growth phase, and to the metastatic phase." (PMID 20631829, 2010). "Additionally, we found that atezolizumab and bevacizumab extended the PFS and OS of NRAS mutant patients to levels similar to those of wild‐type patients, and NRAS mutant mucosal melanoma exhibiting enhanced angiogenesis feature with elevated VEGFA expression." (PMID 39757723, 2025). "Furthermore, differential expression analysis revealed upregulation of genes such as PTK2, PRG2, and VEGFA in tumor samples compared to normal skin, alongside downregulation of other ARGs—reinforcing their involvement in melanoma pathogenesis." (PMID 40943183, 2025). "In agreement with our results, MIR205HG has been demonstrated to accelerate the proliferation of melanoma cells by inducing the canonical oncogenic Wnt/β-catenin signaling pathway and support melanoma tumor growth by mediating the miR-299-3p/vascular endothelial growth factor A axis." (PMID 38252669, 2024). "Furthermore, serum VEGFA levels in melanoma patients vary from 100–500 pg/ml, values dependent on the disease stage." (PMID 38148112, 2024).
melanoma (continued). "The VEGFA-resistant vascular barrier in the Vegfr2Y949F/Y949F mouse blood vasculature correlates with decreased hematological metastastatic spread from RipTag2 neuroendocrine tumors or B16F10 melanoma." (PMID 38148112, 2024). "Our group, recently showed that the simultaneous BRAF/VEGFA targeting, induced the tumor infiltration of M1 macrophages, with a mandatory role in determining the delay of acquired resistance to BRAFi in a A375 melanoma model." (PMID 37183363, 2023). "The reconstitution of vascular mimicry with the combination of VEGFA signaling in ECM contributes to the formation of capillary-like structures in the melanoma microenvironment which is regulated by intracellular and extracellular Ca2+ levels and ανβ3 and ανβ5 integrins." (PMID 35162934, 2022). "Serum analysis of human melanoma cells demonstrated the high expression of VEGFA, which could be utilised to monitor different melanoma stages." (PMID 36077754, 2022). "Moreover, assessment of brain metastasis from malignant melanoma revealed low vascular endothelial growth factor-A (VEGF-A) expression in the parenchyma, which led to an infiltrative phenotype, in which the pre-existing vasculature of the brain was co-opted." (PMID 36119528, 2022). "However, there were differences in the cytokine profile up-regulated regarding the MP polarization profile; MP-GM/melanoma produced more TNF and CCL20, whereas MP-M/melanoma produced more VEGFA." (PMID 34439098, 2021). "Since VEGFA is involved in tumorigenesis of melanoma, it was selected for further analysis." (PMID 33535182, 2021). "We demonstrated that VEGFA was a direct target of miR-299-3p in the melanoma cells." (PMID 33535182, 2021). "In addition, miR-299-3p mimics significantly inhibited the expression of VEGFA in melanoma cells in a dose-dependent manner." (PMID 33535182, 2021). "As an example for the “seed” aspect, melanoma cells were shown to recruit preexisting vessels in the brain parenchyma (vessel-cooption) whereas pulmonary cancer cells induce neoangiogenesis mediated by vascular endothelial growth factor A." (PMID 32065345, 2020). "In a preclinic mouse model with multiple cancer cell lines including melanoma, DeAlmeida and Colleagues demonstrated that therapy with anti-VEGFA targeting agent induces the HIF1α-mediated activation of intratumoral CD8+ cells resulting in an increase in IFNγ and TNFα production." (PMID 33193402, 2020). "Importantly, we found that melanoma cells overexpressing kindlin-2 promoted angiogenesis and VEGFA secretion in vitro and facilitated tumour growth and lung metastasis in vivo." (PMID 31427543, 2019). "Finally, CD63, a well-known melanoma-associated antigen (also called “Melanoma-Associated Antigen ME491”), has a role in VEGFA signaling." (PMID 31921654, 2019). "In line with this interpretation, excessive angiogenesis, a hallmark of melanoma, and the progression from a radial growth phase to a vertical growth phase has been shown to require high angiogenic activity dependent on FGF1, FGF2 and VEGFA." (PMID 29666124, 2018). "Similarly, increased VEGFA expression correlates with greater metastatic potential of melanoma, and its expression is high in melanoma metastases themselves." (PMID 23166713, 2012). "Therefore, we believe that the VEGFA expression comes from melanoma cells." (PMID 41168392, 2025). "BRO melanoma cells, where G0‐positive cells increased following dacarbazine treatment, were characterized by a similar signaling pathways pattern dysregulation, where the ‘VEGFA‐VEGFR2’ signaling pathway was the most altered, with 118 genes downregulated upon dacarbazine treatment and 6 upregulated." (PMID 36533319, 2023). "As one of the main members of VEGF, VEGFA could also mediate VM and angiogenesis in melanoma cells." (PMID 35379271, 2022).
melanoma (continued). "Hence, VEGFA/VEGFR1 pathway was considered to contribute to the formation of VM in melanoma." (PMID 30945361, 2019). "In melanoma, CTLA-4 and vascular endothelial growth factor A blockade elicited a humoral response to Galectin-3 that correlated with improved patient outcomes." (PMID 41477833, 2026). "Fourteen overlapping targets (GSK3B, MAPK1, HSPA8, VEGFA, FGF2, MTOR, and so on) were considered potential targets for the treatment of melanoma with salidroside." (PMID 40708947, 2025). "We compared the expressions of EGFR, VEGFA, and HIF1A in a subset of patients that included the 30 patients with thyroid cancer and 32 patients with melanoma for whom expression data was available." (PMID 40869231, 2025). "It has also been shown that miRNA-126-3p down-regulation contributes to dabrafenib-acquired resistance in melanoma patients by up-regulating ADAM9 (ADAM Metallopeptidase Domain 9) and VEGFA." (PMID 38469304, 2024). "The tumor contents of VEGFA and VEGF receptor VEGFR2 are higher in malignant melanomas vs benign nevi and in metastatic vs primary melanomas." (PMID 36539575, 2023). "Given that VEGFA, TGFβ1, CCL5 and CXCL2 are released in cell media (CM) as soluble factors, we collected the supernatants from drug resistant A375 and M14 melanoma cells and from their sensitive counterparts." (PMID 36418472, 2023). "Numerous investigations into this process have led to the detection of angiogenesis-promoting molecules produced by TAMs, including vascular endothelial growth factor-A (VEGF-A) in the context of non-small cell lung cancer and adrenomedullin in melanoma." (PMID 37429944, 2023). "Undermining IPRES by blocking the activity of its key pathways, VEGFA and TGF-β, has robust potential to improve clinical outcomes of patients with melanoma treated with ICB." (PMID 35577211, 2022). "Vascular endothelial growth factor A (VEGF-A) and its receptors (VEGFR1 and R2) play important roles in the progression of malignant melanoma through tumor angiogenesis." (PMID 35997849, 2022). "The analysis of the melanoma cell secretome indicated that CHI3L1 increases the abundance of various cytokines, such as CC-chemokine ligand 2 (CCL2), and growth factors, such as vascular endothelial growth factor A (VEGF-A)." (PMID 33920100, 2021). "Our results highlight the role of TAMs in biologically aggressive primary melanomas, suggesting that prometastatic TAMs are characterized by higher secretion of CCL20/TNF/VEGFA cytokines." (PMID 34439098, 2021). "Using monocyte-derived macrophages, with either GM-CSF or with M-CSF, which are known to prime towards M1 or M2 phenotypes, we produced in vitro melanoma-conditioned macrophages expressing CCL20 and TNF (M1-primed) or VEGFA (M2-primed)." (PMID 34439098, 2021). "The acquisition of an HIF1/NFkB-directed proinflammatory phenotype was characterized by the induced production and release of several factors, including TNFα, CCL5, IL6, VEGFA, CXCL8, PGE2 and CCL2, which had a prosurvival effect on melanoma cells." (PMID 32967672, 2020). "We used a mouse melanoma cell line, B16F10, to analyze the role of the UV–ATM–SerRS pathway in regulating VEGFA and tumor angiogenesis." (PMID 31766690, 2019). "Among them, vascular endothelial growth factor A (VEGFA) exerts an important role in endothelial cell proliferation and vascular remodelling by activating its tyrosine kinase receptor (VEGFR) in melanoma." (PMID 31427543, 2019). "CAFs exhibit increasing expressions and secretion of VEGFa, FGF2, and MMP9, promoting proliferation, migration, and tube formation of ECs, and melanoma angiogenesis." (PMID 30285793, 2018). "Vascular endothelial growth factor A (VEGF-A) and IL-6, in particular, promote accelerated growth and infiltration of melanoma cell lines in vitro with accompanying co-optation of peritumoral vessels and increased vascular permeability." (PMID 29179523, 2017).
melanoma (continued). "Neuropilin-1 (NRP-1), a co-receptor for vascular endothelial growth factor-A (VEGF-A) tyrosine kinase receptors (VEGFRs), has been suggested to play a relevant role in melanoma progression." (PMID 28977999, 2017). "There was a statistically significant increase in the expression of VEGFA, OCT4 and Snail1 when the cells were grown under hypoxic conditions compared to cells grown under normoxic conditions in all three melanoma cell lines tested." (PMID 29383148, 2017). "To ensure that it was indeed the melanoma cells expressing high levels of VEGFA and not endothelial cells of the blood vessels, we first evaluated the expression of VEGFA and an endothelial cell marker PECAM1 across all ROIs." (PMID 41168392, 2025). "Notably, VEGFA and SPP1 were significant prognosticators both in primary and metastatic tumors, underscoring their broader role in melanoma progression." (PMID 40943183, 2025). "Furthermore, activation of eNOS was suppressed in VEGFA-stimulated iECs from Vegfr2Y1173F/+ mice, relative to iECs from WT mice, as well as in tumor vessels in B16F10 melanoma growing in Vegfr2 Y1173F/+ mice." (PMID 37651195, 2023). "In melanoma, the lncRNA MIR205HG promotes tumor growth and invasion via miR-299-3p/VEGFA axis." (PMID 37189408, 2023). "Several of the EMT-related genes with higher expression in NR patients encoded for molecules controlling adhesion (ITGB3, VCAM1, collagens, and others), interaction with extracellular matrix (VEGFA, MMP14, WNT5A, LAMA1, and others), and melanoma de-differentiation (KRT9, KRT10, EGFR, and others)." (PMID 37739939, 2023). "The authors report that BRAF/VEGFA targeting reverses immune cell exclusion by increasing the infiltration of CD8 T cells and M1–macrophages, allowing remodeling of the tumor microenvironment and sensitizing melanoma cells to immune checkpoint blockade." (PMID 37183363, 2023). "In contrast, VEGFA, TGFβ receptor, NLRP3 inflammasome and Oncostatin M signaling were selectively upregulated, while antigen processing and pattern recognition receptor activity genes were downregulated in melanoma mDC." (PMID 37938561, 2023). "Anti-angiogenic blocking antibodies against VEGFA prevent angiogenesis, but not vessel co-option and melanoma brain metastasis." (PMID 36077754, 2022). "Exosomal miR-155-5p derived from melanoma could induce fibroblasts to express proangiogenic factors such as VEGFa, FGF2 and others, giving novel strategies to suppress melanoma proliferation through increased cytokine signaling." (PMID 34900338, 2022). "We further demonstrated that pathway genes differentially expressed between Black and White individuals, including VEGFA, APOE, and FGFR, are expressed by mouse melanocytes and mouse melanoma cells, where their levels are directly modulated by the degree of pigmentation." (PMID 33983985, 2021). "Similarly, we now observed up-regulation of TNF and VEGFA mRNA expression by melanoma-conditioned MP-GM(BLM) and, to a lesser amount, by MP-M(BLM), which were separated from BLM melanoma cells after co-culture." (PMID 34439098, 2021). "Another study elucidated that chitinase 3-like 1 (CHI3L1), an enzymatically inactive mammalian chitinase, interacts with the extracellular matrix of melanoma cells, increasing the secretion of various cytokines, such as CCL2, and growth factors, such as vascular endothelial growth factor A (VEGF-A)." (PMID 34885161, 2021). "Significantly, higher contents of the intracellular cytokines CCL20, TNF, and VEGFA were quantified in TAMs infiltrating metastasizing compared to non-metastasizing skin primary melanomas (p < 0.001)." (PMID 34439098, 2021). "Melanoma TAMs were also characterized in situ by their high content of CCL20, TNF, and VEGFA by multicolor immunofluorescence in cryopreserved samples; we now show that this particular cytokine profile may be detected and quantified in diagnostic FFPE." (PMID 34439098, 2021).
melanoma (continued). "In RUNT KO melanoma cells, reduced expression of genes involved in metastatic processes (e.g., CD31, MMP9 and VEGFA) was observed, and genes involved in promoting bone metastasis, such as IBSP (coding for bone sialoprotein) and SPP1 (coding for osteopontin), were downregulated." (PMID 32204402, 2020). "Interestingly, in the presence of IFNγ and TNFα melanoma cells can also upregulate TGFB, IL10, VEGFA, and VEGFC genes, which can further modulate the immunosuppressive phenotype of TAMs." (PMID 32793228, 2020). "Various antiangiogenic drugs targeting the VEGFA pathway have been evaluated in clinical trials but none of the drugs have improved survival for patients with malignant melanoma." (PMID 29183378, 2017). "In contrast, restricting VEGFA-induced permeability alone as in the Vegfr2Y949F/Y949F genotype, failed to suppress inflammatory cell infiltration in RIP1-TAg2 insulinomas and B16F10 melanomas." (PMID 27005951, 2016). "Since vascular endothelial growth factor A (VEGF-A) plays a key role in angiogenesis and is expressed in a high proportion of melanomas, we conducted a clinical trial with bevacizumab monotherapy, a humanized monoclonal antibody that binds specifically to VEGF-A, in patients with metastatic CMM." (PMID 27166673, 2016). "Furthermore, several vascular regulators reduced in SHP2-silenced mouse B16F10 cells and tumors were expressed at significantly higher levels in metastatic compared with primary human melanomas, including ANGPT1, THSB2 (codes for thrombospondin 2), PTX3, FGF7 (also known as KGF), and VEGFA." (PMID 40131370, 2025). "Finally, we observed a significant negative Spearman correlation (r = −0.4021; p = 0.0376) between the two Down-miRs (i.e. miR-204-5p and miR-199b-5p) and the four Up-genes (i.e. VEGFA, TGFβ1, CCL5 and CXCL2) only in melanoma biopsies progressed after targeted therapies (PD samples)." (PMID 36418472, 2023). "Interestingly, EVP numbers were not affected when anti-VEGFA treatment was used to reduce melanoma vascularization." (PMID 36077754, 2022). "In addition, among the genes indirectly regulated by miR-146a through NFkB activity, we found CCL2, IL6, and VEGFA, which contribute to the proinflammatory phenotype, CD274 (PDL1), which promotes melanoma cell proliferation, and BCL2L1 and MCL1 antiapoptotic genes." (PMID 32967672, 2020). "Notably, miR-146a upregulation with concomitant increased COX2, PDL1, VEGFA, CCL2, IL6, IL8 and MCL1 expression characterized the MDSCs induced in vitro by melanoma extracellular vesicles from monocytes from healthy donors, suggesting cell type-specific regulation of the miR-146a/COX2 axis." (PMID 32967672, 2020). "Furthermore, fibroblasts activated by melanoma cells showed upregulation of the MMPs’ expression mediators’ levels (pERK, p-p38, CD44, RUNX), enhanced secretion of lactate, several cytokines (IL8, IL6, CXCL1, CCL2, ICAM1), and proteins related to angiogenesis (GM-CSF, DPPIV, VEGFA, PIGF)." (PMID 35538545, 2022). "However, the relationship between miR-299-3p and VEGFA has not been established in melanoma." (PMID 33535182, 2021). "Melanoma BLM cells were also analyzed after co-culture, showing no expression of CCL20 and low induction of TNF mRNA, whereas VEGFA mRNA was basally expressed by BLM cells." (PMID 34439098, 2021). "Moreover, we only focused on the role of the VEGFA/EMT axis and did not investigate the involvement of other pathways involved in melanoma progression." (PMID 33535182, 2021). "To explore the effect of targeting these pathways during co-cultures of MPs (GM and M) with melanoma cells, we used BLM and A375 (which do not express VEGFA basally) metastatic melanoma cell lines, which similarly induced secretion of the three cytokines in the co-cultures." (PMID 34439098, 2021).
melanoma (continued). "Conversely, increased VM was observed in an in vivo model where melanoma cell line WM1617 infected with VEGFA siRNA was introduced into SCID mice; however, use of other melanoma cell lines C8161 and A2058 did not result in any difference in VM in this in vivo model." (PMID 29104239, 2017).